SOCS3 (suppressor of cytokine signaling 3)
Diseases named in the same sentence as SOCS3 in open-access papers (continued):
Sharing a sentence is not in itself a finding about the gene and the disease.
COVID-19 (continued). "Individuals in the COVID-19 group showed higher expression of OAS1 (p = 0.0002), MAVS (p = 0.0001) and SOCS3 transcripts (p = 0.001) as compared to HC." (PMID 41468475, 2025). "This in silico model predicted that five genes important for embryo implantation were affected by COVID-19 (down-regulation of COBL, GPX3 and SOCS3, and up-regulation of DOCK2 and SLC2A3)." (PMID 38372528, 2024). "Intriguingly, cross-sectional analysis reveals the opposite correlation between ISGs and disease severity: SOCS3 and other IFN-suppressing factors were upregulated in severe COVID-19." (PMID 38238298, 2024). "In the COVID-19 cohort, IL6, PTSG2, JUN, ATF3, SOCS3, CSF3, and NFKB2 had AUC values greater than 0.7." (PMID 36380355, 2022). "Further, they observed that key driver genes, which were upregulated with COVID-19 and IBD inflammation (e.g., CXCL1, GBP4, SOCS3, PARP14, and PARP9), were downregulated following the use of infliximab." (PMID 36060521, 2022). "Eight ISGs were downregulated in Asymptomatic as compared with severe COVID-19 cases; CNP, CSF1, IRF1, IFITM10, IRF2BP2, IRF2BPL, SLC25A28 and SOCS3." (PMID 34824360, 2021). "Of these, nine ISGs were differentially regulated in Asymptomatic versus mild COVID-19 cases; IFNAR2, IRF2BP1, IRF4, MAVS, and TRIM14 were upregulated; whilst IRF2BP2, IRF2BPL, and SOCS3 were downregulated." (PMID 34824360, 2021). "COVID-19 cases displayed higher expression of mRNA levels of MAVS, OAS-1, and SOCS3 (p < 0.05)." (PMID 41468475, 2025). "On the other hand, the suppressor of cytokine signaling 3 (SOCS3) pathway, which has negative feedback on IL-6 production, is downregulated during COVID-19, thus contributing to IL-6 hyper-production." (PMID 35572540, 2022). "Concordantly, for downstream genes of AP-1, the expression levels of some chemokine genes (e.g., CCL2, CXCL1, CXCL2, and CXCL10) were downregulated, while the expression levels of immune negative regulation genes (e.g. BCL3, NFKBIA, SOCS3, and TNFAIP3) were upregulated during the COVID-19 recovery." (PMID 33361761, 2020). "Moreover, COVID-19 neutrophils expressed higher amounts of ISG15 and decreased levels of suppressor of cytokine signaling 3 (SOCS3) mRNA upon IFNα stimulation." (PMID 33003471, 2020). "Moreover, qRT-PCR analysis of the whole RNA extracted from the blood serum of severe COVID-19 patients with pulmonary and extrapulmonary findings, confirmed the significant elevation in the gene expression of TRIM56 and SOCS3 in response to extrapulmonary dysfunction in severe COVID-19 patients." (PMID 34262555, 2021).
glioblastoma (22 papers, 2014 to 2026). The most malignant astrocytic tumor (WHO grade IV). "It is worth mentioning that SOCS3 expression levels were negatively relevant to CTL in glioblastoma patients, which indicated an interaction with T-cell exclusion." (PMID 35600392, 2022). "As SOCS1 and SOCS3 have been involved in response to radiation in glioblastoma, clonogenic assays were performed to evaluate the possible contribution of SOCS gene expression to radioresponsivity." (PMID 25849377, 2015). "The miR-221/222 cluster may affect the angiogenic process in glioblastoma cells by regulating the activation of the JAK/STAT pathway through the regulation of the suppressor of cytokine signaling-3 (SOCS3)." (PMID 36479040, 2022). "Interestingly, SOCS1 sensitizes glioblastoma cells to radiation, whereas SOCS3 enhances tumor cell survival and radioresistance." (PMID 25849377, 2015). "High SOCS3 expression in glioblastoma multiforme (GBM) and brain lower-grade glioma (LGG) were verified through immunohistochemical experiments." (PMID 35600392, 2022). "PBMCs from glioblastoma patients exhibited increased expression of the regulatory genes SOCS1, SOCS3, and PTEN, while CCND1 was downregulated." (PMID 41898348, 2026). "Among which, CDC73, PSMC2, SOCS3, and ETV4 were substantially upregulated; whereas PLK2 and LMO7 were substantially downregulated in glioblastoma cells than that in control." (PMID 41318472, 2025). "The expression of SOCS1 and SOCS3 in glioblastoma (GBM) cells is decreased." (PMID 36835292, 2023). "Conversely, radioresistant glioblastoma (GBM) highly expresses negative regulators of the IFN–JAK–STAT signaling (SOCS1 and SOCS3) and attenuates IFN–JAK–STAT signaling." (PMID 34830176, 2021). "We noted an overlap of up-regulated genes with an immune signature reported in a glioblastoma profiling study, including MHC class I and II genes, the complement factors C1QA/B/C, FCGR3A, B2M, SOCS3, TLR2 and CTSH." (PMID 25593989, 2014). "Interestingly, it was found that in glioblastoma (GBM) cell lines, SOCS1 and SOCS3 are regulated reciprocally and SOCS3 is highly expressed in GBM, while SOCS1 is not." (PMID 31632280, 2019).
Hyperglycemia (21 papers, 2013 to 2024). An increased concentration of glucose in the blood. "We previously reported that the increase of SOCS3 and TNFα, in hyperglycemia, is associated with increased levels of IRS-1Ser307 phosphorylation and decreased phosphorylation of IRTyr1150/1151, leading to inhibition of normal insulin signaling." (PMID 25888955, 2015). "Chronic hyperglycaemia has been shown to upregulate the signalling molecule suppressor of cytokine signalling 3 (SOCS3), a protein usually involved in the suppression of inflammation." (PMID 36564054, 2023). "Another study showed that overexpression of SOCS3 protects against hyperglycemia-induced epithelial cell injury by inhibition of the JAK2-STAT3 pathway." (PMID 33372035, 2021). "In contrast, the cells cultivated in normoxia and hyperglycemia exhibited an upregulation of SOCS-3." (PMID 31415598, 2019). "As SOCS-3 is upregulated in this study, this confirms the inflammatory effect of IL-6 in hyperglycemia." (PMID 31415598, 2019). "HG-increased SOCS-3 expression was associated with STAT1/3, suggesting a possible innovative transcriptional mechanism for hyperglycemia-induced ECM accumulation." (PMID 28129651, 2017). "Similar effects were seen in retinal endothelial cells, where hyperglycaemia caused elevated TNF-α, increased IRS1Ser307 phosphorylation and loss of IRS1 protein, likely via suppressor of cytokine signalling 3 (SOCS3)-mediated targeting to the proteasome." (PMID 27514532, 2016). "We, therefore, demonstrated that miR-15b and miR-15b/16 play a role in suppressing SOCS3 signaling in REC in hyperglycemia." (PMID 25888955, 2015). "In the present study, we demonstrated that an increased level of miR-15b and/or miR-16 in REC resulted in decreased signaling of TNFα and SOCS3, indicating the role of the microRNAs as regulators of these cytokine pathways in response to hyperglycemia." (PMID 25888955, 2015). "Overexpression of miR-15b and miR-15b/16 significantly reduced the levels of SOCS3 in hyperglycemia." (PMID 25888955, 2015). "In fact, it is well known that SOCS3 is modulated by oxidative stress in response to hyperglycemia and the TNF-α production is induced by H2O2 via oxidative stress-related signal pathways." (PMID 23533689, 2013). "Data from other targets suggest that hyperglycemia-induced TNFα can activate SOCS3, leading to impaired insulin signaling." (PMID 23592917, 2013). "Pae inhibits MMP-9 expression and the inflammatory response in hyperglycemia-induced retinal microglia via inhibition of the TLR4/NF-κB signaling pathway, through the upregulation of suppressor of cytokine signaling 3 in diabetic retinopathy." (PMID 35184653, 2022). "In recent years, an increasing number of studies have demonstrated that SOCS3 and STAT3 mediate inflammation, apoptosis, and insulin signalling in hyperglycaemia-stimulated retinal endothelial cells." (PMID 29318137, 2017). "Thus, we examined whether miR-15b and miR-16 alter SOCS3 levels in hyperglycemia." (PMID 25888955, 2015). "In addition to hyperglycemia, TNF-α (Th1 cytokine) also reported to directly induce SOCS3 expression." (PMID 29572460, 2018). "Overexpression of miR-15b and/or miR-16 reduced TNFα and SOCS3 levels, while increasing insulin-like growth factor binding protein-3 (IGFBP-3) levels and the phosphorylation of insulin receptor (IR)Tyr1150/1151 in REC cultured in hyperglycemia." (PMID 25888955, 2015). "That suggests that miR-15b may directly or indirectly target IGFBP-3, which contributed to the reduced signaling of TNFα and SOCS3, as well as increased IRTyr1150/1151 phosphorylation to protect REC in hyperglycemia." (PMID 25888955, 2015). "Hyperglycemia seems to have a short term negative effect on SOCS3." (PMID 31415598, 2019). "Thus, we speculated that HXJD might ameliorate hyperglycaemia-induced apoptosis and VEGF in the retinas of diabetic rats through controlling SOCS3 or STAT3 expression." (PMID 29318137, 2017).
Hyperglycemia (continued). "In the present study, we tested the hypothesis that miR-15b and miR-16 levels are altered by exposure to hyperglycemia in REC, and that miR-15b/16 play key roles in regulating insulin signaling through a reduction in TNFα- and SOCS3-mediated insulin resistance pathways." (PMID 25888955, 2015).
liver cancer (21 papers, 2010 to 2025). An epithelial or non-epithelial malignant neoplasm that arises from the liver. "In order to examine whether SOCS3 mRNA expression was associated with the development of liver cancer, we analyzed SOCS3 mRNA expression according to the BCLC staging classification." (PMID 28179578, 2017). "Based on the TIMER database, we observed a significant downregulation of SOCS3 in liver cancer tissues compared to normal liver tissues." (PMID 39940889, 2025). "Further analysis and experimental validation demonstrated that upregulated DNMT3a in liver cancer cells promoted SOCS3 promoter hyper-methylation and suppressed SOCS3 expression." (PMID 33234142, 2020). "In summary, these results suggest that, in liver cancer cells, DNMT3a upregulation promotes SOCS3 promoter methylation and suppresses SOCS3 expression, which further activates JAK2/STAT3 signaling pathway." (PMID 33234142, 2020). "Consistently, the potentiation of cell death induced in liver cancer cell cultures by the combined treatment with taxol and TNFα was associated with reduced levels of both phosphorylated STAT3 and SOCS3, one of the STAT3 target genes." (PMID 31653043, 2019). "SOCS3 silencing by promoter methylation is possibly involved in the progression of HBV-related liver cancer." (PMID 28179578, 2017). "Moreover, we found a negative correlation between SOCS3 expression and the malignancy grade of liver cancer, whereas a positive correlation was observed between SOCS3 expression and FXR levels." (PMID 39940889, 2025). "Importantly, liver cancer patientssuffering from high-grading metastasis showed obviously lower levels of SOCS3 expression." (PMID 34450627, 2021). "First, SOCS3 expressionin liver cancer tissues was much lower than that in normal liver tissues." (PMID 34450627, 2021). "We then explored whether the downregulation of SOCS3 by B[a]P exposure-induced miR-650aexpression correlates with liver cancer progression in patients." (PMID 34450627, 2021). "In addition, our previous study demonstrated that Gab2 could interact with PI3K, Socs3, and Shp2 in HepG2 cells upon treatment with ethanol or oleic acid, which were also the carcinogenic factors of liver cancer." (PMID 28842424, 2017). "SOCS1 alterations through SOCS7 and CISH alterations were detected in liver cancer tissues at the following frequencies: SOCS1, 1.1%; SOCS2, 0.8%; SOCS3, 6%; SOCS4, 0.3%; SOCS5, 1.3%; SOCS6, 1.3%; SOCS7, 2.4%; and CISH, 2.7%." (PMID 39307915, 2024). "The constitutive activation of STAT3 in liver cancer is frequently due to the aberrant methylation and silencing of Suppressor of Cytokine signaling-1 (SOCS-1) and -3 (SOCS-3)." (PMID 20712901, 2010). "Therefore, our findings suggested that reduced SOCS3 expression coupled with enhanced STAT3 phosphorylation activated the IL6/JAK/STAT signaling pathway, resulting in an elevated incidence of primary liver cancer in FXR−/− mice." (PMID 39940889, 2025). "For example, hepatitis B virus (HBV) infection could induce the accumulation of mitochondrial reactive oxygen species (ROS), thereby inhibiting the expression of suppressor of cytokine signaling 3 (SOCS3) and activating the interleukin-6 (IL-6)/STAT3 pathway, ultimately leading to liver cancer." (PMID 32735635, 2020).
rheumatoid arthritis (21 papers, 2013 to 2025). A chronic, systemic autoimmune disorder characterized by inflammation in the synovial membranes and articular surfaces. "Several studies have shown that the expression and function of SOCS3 in chondrocytes play critical roles in preventing cartilage loss in conditions such as osteoarthritis (OA) and rheumatoid arthritis (RA)." (PMID 24454312, 2014). "However, decreased expression of SOCS3 is associated with the development of other inflammatory conditions, such as acute lung injury, hypersensitivity, and rheumatoid arthritis." (PMID 36969252, 2023). "Dysregulated expression of SOCS3 has been frequently observed in various forms of inflammatory disorders, such as rheumatoid arthritis and Crohn’s disease, with SOCS1 haploinsufficiency shown to predispose to early onset autoimmune disease." (PMID 36969252, 2023). "We highlight six tocilizumab responsive genes (ARID5A, BCL3, PIM1, SOCS3, BATF, MYC) that are associated with IL-6 pathway and known to be perturbed by tocilizumab treatment in rheumatoid arthritis patients." (PMID 35064122, 2022). "STAT5 activation and SOCS-3 have also been reported to be involved in collagen-induced arthritis (CIA) in a well-established mouse model of rheumatoid arthritis (RA)." (PMID 29534522, 2018). "On the other hand, enhanced IL-6 responses accounted for the enhanced susceptibility of Socs3fl/flvav cre or Socs3fl/flLysM cre (deficient in SOCS3 in myeloid cells) mice to induced inflammatory diseases like rheumatoid arthritis (RA) or experimental autoimmune encephalomyelitis (EAE)." (PMID 24600449, 2014). "For example, it was shown to effectively inhibit Receptor activator of nuclear factor-κB ligand (RANKL) expression by inhibiting the JAK2/STAT3 pathway and upregulating SOCS3 in rheumatoid arthritis fibroblast-like synoviocytes (FLS) stimulated with IL-6/sIL-6R." (PMID 39769302, 2024). "Suppressor of cytokine signaling-3 (SOCS3) is an important regulator of various cell functions, that can regulate the production of cytokines and is closely related to the pathogenesis of diseases such as rheumatoid arthritis." (PMID 37880626, 2023). "Local elevation of SOCS3 expression in vivo has already been shown to have beneficial effects on limiting inflammatory cell infiltration and the ensuing tissue dysfunction in mouse models of specific inflammatory diseases, including systemic bacterial infection, hepatitis, and rheumatoid arthritis." (PMID 24886706, 2014). "This study aimed to further investigate the correlation between three effective biomarkers (JUN, SOCS3, CXCL8) and immune infiltrating cells, which play a crucial role in rheumatoid arthritis (RA), specifically in RF-negative pJIA and oJIA." (PMID 38001449, 2023). "It is proposed that the ability of YSTB to slow the progression of rheumatoid arthritis may be related to modulating the JAK/STAT pathway by degrading the phosphorylated expression of JAK2, JAK3, and STAT3 proteins, whereas elevated SOCS3 protein expression." (PMID 38966637, 2024). "For example, in the mBSA model of rheumatoid arthritis (RA), proinflammatory responses were elevated in the absence of SOCS3 in the hematopoietic and endothelial cell compartment." (PMID 26579124, 2015). "In Rheumatoid Arthritis (RA), aberrant upregulation of SOCS1 and SOCS3 has been documented in peripheral blood T lymphocytes, monocytes, and synovial tissues, with expression levels correlating with disease activity and progression." (PMID 41393140, 2025). "The expression of RANKL, JAK2, STAT3, and SOCS3 proteins was assessed by western blot analysis, real-time PCR and ELISA in IL-6 combined with soluble IL-6 receptor (sIL-6R)-stimulated rheumatoid arthritis (RA)-FLS with or without tacrolimus treatment." (PMID 23406906, 2013).
rheumatoid arthritis (continued). "IL-6, as a pro-inflammatory cytokine, has been proposed to contribute to the progression of rheumatoid arthritis and Crohn's disease, while SOCS3 is a major negative regulator of the IL-6-related cytokine-STAT3 pathway and enhanced expression of SOCS3 inhibits these inflammatory responses." (PMID 33281724, 2020).